SP1 (Sp1 transcription factor)
Diseases named in the same sentence as SP1 in open-access papers (continued):
Sharing a sentence is not in itself a finding about the gene and the disease.
osteosarcoma (43 papers, 2012 to 2025). A usually aggressive malignant bone-forming mesenchymal neoplasm, predominantly affecting adolescents and young adults. "We have consistently shown that Sp1 was elevated in osteosarcomas and was associated with the nuclear grade (p = 0.024), but not with the survival of the patients." (PMID 29088790, 2017). "Considering the biological significance of PLD1 in osteosarcomas, and the fact that Sp1 could transcriptionally activate genes associating with malignant phenotypes, we postulated that the two factors were positively correlated." (PMID 29088790, 2017). "Since PLD1, which was also associated with the malignant phenotype of osteosarcomas, was positively correlated with Sp1, further studies are required to determine the potential role of targeted inhibition of PLD1 without/or in combination with Sp1 as an candidate therapeutic target in clinics." (PMID 29088790, 2017). "We found that SP1 was significantly downregulated at both mRNA and protein levels in osteosarcoma cells treated with HDAC inhibitors." (PMID 37457661, 2023). "In this study, we found that GABPB1-AS1 promotes the development of osteosarcoma by targeting SP1 to activate the Wnt/β-catenin pathway." (PMID 35342417, 2022). "Further studies on the role of SP1 and its related signaling pathways in osteosarcoma will be helpful to further understand the mechanism of osteosarcoma occurrence and metastasis." (PMID 35342417, 2022). "In conclusion, our study provides mechanistic insights into the oncogenic effect of CLTC, and understanding of the SP1/CLTC/TFG axis serves a novel therapeutic strategy for patients with osteosarcoma." (PMID 34185412, 2021). "Intriguingly, lncRNA CRNDE was activated by sp1 to enhance osteosarcoma cell epithelial-mesenchymal transition via the Wnt/β-catenin signaling." (PMID 34499009, 2021). "SP1 knockdown osteosarcoma cells showed lower mRNA and protein levels of CLTC than that in the control cells in our study." (PMID 34185412, 2021). "In osteosarcoma, ILF3-AS1 was induced by SP1 and promoted the proliferation, migration and invasion of osteosarcoma cells through miR-212/SOX5 axis." (PMID 32117452, 2020). "We also revealed that PLD1 was positively correlated with Sp1- a factor that was also elevated in osteosarcomas." (PMID 29088790, 2017). "In this study, We found that PLD1 and Specificity Protein 1 (Sp1) expression were elevated in 137 osteosarcoma specimens with immunohistochemical staining." (PMID 29088790, 2017). "In U-2 OS osteosarcoma cells, HIF-1α can directly associate with Sp1 via its N-terminal PAS domain region, whereas Sp1 interaction with HIF-2α is prevented because the threonine 324 residue within the PAS domain is phosphorylated by protein kinase D1." (PMID 26703734, 2015). "Interestingly, the zinc finger and glutamine domains of SP1 act as copper sensors, suggesting its therapeutic potential for copper-induced cell death in osteosarcoma." (PMID 41323391, 2025). "Mechanism studies showed that lncRNA GABPB1-AS1, as a competitive endogenous RNA, upregulated the expression of SP1 and promoted the Wnt/β-catenin pathway through sponge adsorption of miR-199a-3p, ultimately promoting the proliferation and malignant evolution of osteosarcoma." (PMID 35342417, 2022). "GABPB1-AS1 mediated osteosarcoma cells via the SP1/Wnt/β-catenin signaling pathway." (PMID 35342417, 2022). "It was also found that silencing of GABPB1-AS1 could significantly inhibit the proliferation, clonal formation, migration, and epithelial-mesenchymal transformation of osteosarcoma by acting the SP1/Wnt/β-catenin signaling pathway." (PMID 37304650, 2021). "SP1 binds to the CLTC promoter to promote the transcriptional activity of CLTC in osteosarcoma." (PMID 34185412, 2021). "Down‐regulation of SP1 inhibited cell proliferation in osteosarcoma." (PMID 34185412, 2021). "SP1-related transcriptional regulation of ADAMTS3 gene expression in osteosarcoma cell models." (PMID 32102222, 2020).
osteosarcoma (continued). "In order to test this, we investigated Sp1 expression in osteosarcomas using immunohistochemistry." (PMID 29088790, 2017). "In conclusion, this study shows that (i) Kv7.5 may be a useful therapeutic target in the treatment of canine osteosarcoma; and that (ii) the transcription factor Sp1 may play an important role in modulating Kv7.5 expression." (PMID 24434641, 2014). "The following study confirmed our hypothesis, we demonstrated that PC4 shRNA downregulated MMP9 mainly through SP1 at the transcriptional level by forming the SP1 transcriptional complex, and this may contribute mechanistically to lung metastases in osteosarcoma." (PMID 28881805, 2017). "Specifically, in osteosarcoma cells, the upregulation of SIRPα activates the extracellular signal-regulated kinase (ERK) pathway, leading to the phosphorylation of specificity protein 1 (Sp1) at the threonine 278 site." (PMID 40589735, 2025). "SP1 was also demonstrated to regulate lncRNA LMCD1-AS1 and lncRNA ILF3-AS1 to facilitate osteosarcoma progression." (PMID 35847857, 2022). "They provided the first findings for the SP1-related transcriptional regulation of ADAMTS3 and collagen genes in osteosarcoma cell lines." (PMID 35847857, 2022). "Western blot analysis was used to detect the protein levels of SP1, Wnt, β-catenin, c-Myc, and SOX2 in osteosarcoma cells." (PMID 35342417, 2022). "For example, circ-ITCH reduced SP-1 expression via the PTEN/PI3K/AKT pathway, which suppressed proliferation, migration, and invasion of osteosarcoma cells." (PMID 33795657, 2021). "Previous studies have suggested that transcription factors OCT‐1, AP1, SP1, TNF, SOX2, SOX4, and MYC play an important role in the proliferation of osteosarcoma cells." (PMID 34185412, 2021). "Further studies confirmed that SP1 binds to the CLTC promoter at the −320 to −314‐nt and +167 to +173‐nt loci and promotes the transcriptional activity of CLTC in osteosarcoma." (PMID 34185412, 2021). "In this study, we identified that SP1 binds to the CLTC promoter at the −320 to −314‐nt and +167 to +173‐nt loci and activates CLTC expression in osteosarcoma cells." (PMID 34185412, 2021). "Recently, Zhao and Li showed that transcription factor SP1 induced upregulation of HCP5, which in turn promoted the development of osteosarcoma, whereas inhibition of HCP5 expression reversed cell invasion and epithelial–mesenchymal transition." (PMID 31137555, 2019). "In this study, we looked at the expression and biological significance of Sp1 and PLD1 in osteosarcomas." (PMID 29088790, 2017). "We subsequently confirmed the binding of Sp1 and Sp3 using nuclear extracts from the chondrosarcoma cell line SW1353, the osteosarcoma cell line MG63 and from primary human articular chondrocytes (HACs)." (PMID 23825960, 2013). "Functional tests verified that HCP5 could function as an oncogene in osteosarcoma and was activated by the transcription factor 1 (SP1), convincing that SP1 induced the up-regulation of HCP5, which impacted the development of osteosarcoma." (PMID 34222007, 2021). "Thus, we first revealed the linkage between transcription factor SP1 and CLTC expression in osteosarcoma." (PMID 34185412, 2021).
osteosarcoma (continued). "In osteosarcoma, MIR-493 was reported to inhibit osteosarcoma cell proliferation and invasion through targeting SP1 and therefore MIR-493/SP1 axis may be developed as potential therapeutic targets." (PMID 30474556, 2018). "Since our study found a positive correlation between Sp1 and PLD1, we postulate here that transcription activation might also apply to the positive correlation between Sp1 and PLD1 in osteosarcomas." (PMID 29088790, 2017). "For verification purpose, the Sp1-directed site-specific ChIP was also tested on the osteosarcoma cell lines MNNG, U2-OS and SJ-SA-1 (data not shown)." (PMID 22348285, 2012). "Also, the ubiquitous transcription factor SP1, which is known to regulate MHC class I gene expression both constitutively and in a tissue-specific manner, was shown to upregulate HCP5 expression and induce the development of osteosarcoma." (PMID 31137555, 2019). "Taken together, our data revealed that therapeutic inhibition of PLD1, either without or in combination with Sp1, could provide an alternative approach for the management of osteosarcoma." (PMID 29088790, 2017). "Moreover, nobiletin effectively suppressed SP-1 and CREB expressions, these findings are consistent with those in reports on leukemia cells, cholangiocarcinoma cells and osteosarcoma cells, implicating the importance of NF-κB and CREB in the regulation of MMP-2 and MMP-9 in U2OS and HOS." (PMID 27144433, 2016). "Therefore, SP1 may regulate the expression of CLTC and mediate the proliferation of osteosarcoma." (PMID 34185412, 2021). "Interestingly, we observed that Sp1 expression in osteosarcomas ranged from negative to strong." (PMID 29088790, 2017). "Western blot was used to detect the protein levels of SP1, Wnt, β-catenin, c-Myc, and SOX2 in osteosarcoma cells with or without GABPB1-AS1 silencing." (PMID 35342417, 2022).
leukemia (35 papers, 2012 to 2025). A malignant (clonal) hematologic disorder, involving hematopoietic stem cells and characterized by the presence of primitive or atypical myeloid or lymphoid cells in the bone marrow and the blood. "After ranking the returned results, we found that SP1 was strongly indicated to be associated with leukemia." (PMID 25932650, 2015). "The gene set was enriched for leukemia-associated genes, as well as for the transcriptome regulated by Specificity Protein 1 (SP1)." (PMID 26694754, 2015). "Of note, the in vivo disruption of the Sp1/NFκB association in a mouse model for KIT-driven leukemia results in a strong inhibition of leukemogenesis and suggests that the targeting of the miR-29b/Sp1/NFκb regulatory loop represents a viable therapeutic option in AML." (PMID 24145746, 2013). "Abnormal Sp1 expression and activation are thought to promote the initiation and progression of human cancer, including leukemia." (PMID 39056681, 2024). "For example, it was shown that the miR-29b/Sp1/FUT4 axis promotes the malignant behavior of leukemia stem cells by regulating CD44 through the Wnt/β-catenin pathway." (PMID 39056681, 2024). "A role for caspase-3 activation in Sp1 degradation has been observed in other studies, whereas bortezomib was found to decrease Sp1, Sp3 and Sp4 in leukemia cells, and this was dependent on caspase-8." (PMID 36982239, 2023). "For example, cleavage of Sp1 by a retinoid in liver cancer cells involves induction of caspase-3 and transglutaminase and caspases-2 and 3 in leukemia cells." (PMID 36982239, 2023). "SP1 can modulate the expression of surviving cells through the MAPK signaling pathway to regulate the drug resistance of leukemia stem cells." (PMID 30425701, 2018). "RUNX1, also a cell-type specific protein, has a mode that resembles the RUNX1 motif, one that is a variant and a third that matches SP1, a known RUNX1 co-factor in leukemia." (PMID 29684008, 2018). "In addition, the oncogenic promyelocytic leukemia zinc finger–retinoic acid receptor α (PLZF-RARα) fusion gene inhibited p21 expression through interaction with Sp1 bound to the proximal GC-rich sequences in the p21 gene promoter and also with an RARE." (PMID 39858066, 2025). "The present study revealed that the overexpression of Sp1 activated the DNA-PKcs promoter in U87 cells, which is consistent with another study showed that Sp1 enhances the activity of the DNA-PKcs promoter in daunorubicin-resistant leukemia cell lines (K562/DNR)." (PMID 37445835, 2023). "Moreover, a ubiquitously expressed protein SP1 is important for driving the genetic program that promotes leukaemia in our model system, and this program is assisted by PKCβ." (PMID 36497487, 2022). "The anomalous expression and activation of Sp1 may induce the initiation and development of human cancers such as leukemia." (PMID 34627167, 2021). "In another study, it was ascertained that TQ (15 mg/kg of mouse body weight) through up-regulating miR-29b expression could obstruct the Specificity protein 1 (Sp1)- NF-κB feedback loop in mice bearing leukemia and eventually reduced the rate of tumor growth." (PMID 34627167, 2021). "Interestingly, miR-29b plays a critical role in c-KIT oncogene expression regulation in CBF leukemia by dampening c-KIT oncogene transcription through the direct targeting of its activator Sp1." (PMID 29435107, 2018). "SP1 itself is able to bind the Ah receptor and down-regulates its expression in leukemia cells." (PMID 25364730, 2014). "Sp1 drives basal Axl transcription in solid cancer, but MZF-1 and AP-1 also drive Axl expression in leukemia cells." (PMID 35740998, 2022). "Homoharringtonine exerts antitumor effects by inhibiting the synthesis of target proteins, such as phospho-eIF4E, SP1/TET1/5hmC, Smad3, and TGF-β pathway components, and NF-κB repressing factor, and promotes apoptosis in leukemia cells." (PMID 35873796, 2022).
leukemia (continued). "The microRNA—miR-150, miR-34a, and miR-29b—have also shown significant anti-leukaemia effects by targeting wnt-signalling, mTOR signalling pathways, MYC, and Sp1/FUT4-fucosylations." (PMID 34207299, 2021). "Rothem et al26 have reported that reduced expression of transcription factors as CREB1, ATF1, USF1, FOS, JUN, Sp3, and Sp1 is responsible for a major decrease in RFC mRNA expression in the CCRF‐CEM and derived human leukemia cell lines." (PMID 32614991, 2020). "To confirm these results, we selected three key genes involved in leukemia (interferon-regulatory factor 1 [IRF1], Caspase 8, and specificity protein 1 [SP1]) to confirm the gene expression of those factors was regulated by USP39." (PMID 30898977, 2019). "miR-375 possesses significant anti-leukemia or anti-tumor activity through modulating multiple target genes, including JAK2, SP1, PIK3CA, and AEG-1." (PMID 29439669, 2018). "Further, exposure of leukemia cell lines and patient primary cells to TQ resulted in DNMT1 downregulation, mechanistically, through dissociation of Sp1/NFkB complex from DNMT1 promoter." (PMID 28415607, 2017). "Sp1 forms a complex with NF-κB to downregulate miR-29b expression through the recruitment of histone deacetylase (HDAC) 1 and HDAC3 in leukemia and thereby contributes to the growth of leukemia cells." (PMID 24519909, 2014). "Sp1 is phosphorylated at Ser101 by ATM/ATR in response to DNA damage, and its phosphorylated form transcriptionally regulates the DNA-dependent protein kinase catalytic subunit (DNA-PKcs) in daunorubicin-resistant leukemia cell lines." (PMID 37445835, 2023). "In an investigation, it was revealed that receiving an injection of TQ (15 mg/kg of body weight) in leukemia bearing mice led to down-regulation of the PI3K/AKT signaling network via an Sp1-miR-29b negative feedback loop." (PMID 34627167, 2021). "Pang and colleagues (2017) found that the suppression of Sp1-NF-κB as a result of the triggering effect of TQ on miR-29b led to inactivation of KIT and FLT tyrosine kinases, which are the principal regulators of leukemia." (PMID 34627167, 2021). "Furthermore, we performed a microarray assay and found that USP39 regulated the expression of diverse genes in human leukemia cells, including IRF1, Caspase 8, and SP1, which were validated by qRT-PCR experiments." (PMID 30898977, 2019). "Considering that Sp1/NFkB is also involved in the regulation of receptor tyrosine signaling, we examined the changes of two receptor tyrosine kinases, KIT and FLT3, which play a pivotal role in leukemia pathogenesis." (PMID 28415607, 2017). "SP1 and MYC can modulate drug resistance of leukemia stem cells." (PMID 28684851, 2017). "In leukemia, SIOMICS discovered two shared motifs that were similar to the motifs of MAZ and SP1." (PMID 28684851, 2017). "Because our studies and others demonstrated that Sp1/NFkB is also involved in the regulation of tyrosine kinase signaling, as a proof of concept, we examined the changes of KIT and FLT3, the key regulators of leukemia pathogenesis." (PMID 28415607, 2017). "In particular, the top 3 transcriptional regulation networks showed SP1, c-Myc and HNF4-alpha as central hubs, suggesting that they might play a role in the pathophysiology of BCR-ABL-positive leukemias and/or represent therapeutic targets." (PMID 23460890, 2013). "From our results showing the correlations between Sp1 and c-Myc levels and survivin expression in CD34+ AML patients, inhibitors of Sp1 and c-Myc may provide novel therapeutic strategies for the treatment of leukemia." (PMID 25890196, 2015).